ADIPOQ (adiponectin, C1Q and collagen domain containing)
Diseases named in the same sentence as ADIPOQ in open-access papers (continued):
Sharing a sentence is not in itself a finding about the gene and the disease.
atrial fibrillation (1 paper, 2016). A disorder characterized by an electrocardiographic finding of a supraventricular arrhythmia characterized by the replacement of consistent P waves by rapid oscillations or fibrillatory waves that vary in size, shape and timing and are accompanied by an irregular ventricular response. "Interestingly, serum levels of adiponectin or ADIPOQ gene expression in EpAT were not related with the incidence of postoperative atrial fibrillation (data not shown), which we have previously shown to be increased in patients with high atrial NADPH-oxidases activity." (PMID 26838789, 2016).
autoimmune thyroid disease (1 paper, 2025). Inflammatory disease of the thyroid gland due to autoimmune responses leading to lymphocytic infiltration of the gland. "The GSEA results revealed that ADIPOQ is significantly associated with pathways involved in immune regulation, including B cell receptor signaling and autoimmune thyroid disease." (PMID 40313967, 2025). "ADIPOQ showed significant enrichment in immune regulatory pathways, including B cell receptor signaling and autoimmune thyroid disease, suggesting a potential role in modulating immune responses within the IA microenvironment." (PMID 40313967, 2025).
blood pressure (1 paper, 2022). "Curcumin also lowered adenine-induced high blood pressure, urinary albumin, the inflammatory cytokines interleukins 1 (IL-1) and 6 (IL-6), tumor necrosis factor α (TNF-α), cystatin C (CST3), and adiponectin (ADIPOQ)." (PMID 35910356, 2022).
cardiomyopathy (1 paper, 2017). A disease of the heart muscle or myocardium proper. "Analysis of pathways that were dysregulated across cardiomyopathy phenotypes identified shared genes that were associated with extracellular matrix remodeling and thus likely fibrosis (THY1, CILP, OGN, THBS4, ASPN, HAPLN1,and SMOC2), as well as calcium (ADIPOQ, ASPN, THBS4, STAT4, and SMOC2)." (PMID 28098235, 2017).
chronic hepatitis (1 paper, 2020). An active inflammatory process affecting the liver for more than six months. "Therefore, we can conclude that AdipoQ and leptin levels in patients with chronic hepatitis and cirrhosis have changed compared with healthy controls, which is consistent with Buechler’s conclusion." (PMID 33256658, 2020).
Cirrhosis (1 paper, 2020). A chronic disorder of the liver in which liver tissue becomes scarred and is partially replaced by regenerative nodules and fibrotic tissue resulting in loss of liver function. "Many HCC patients suffer from cirrhosis or fibrosis, both of which are related to the down-regulation of AdipoQ receptors in the liver and the decrease of AdipoQ clearance rate, which leads to AdipoQ resistance state." (PMID 33256658, 2020).
diabetic retinopathy (1 paper, 2024). "Background and Objectives: Recent studies have focused on the association between the risk of diabetic retinopathy (DR) and the rs1501299 and rs2241766 polymorphisms of the ADIPOQ gene; however, their results remain inconclusive." (PMID 39202535, 2024).
Duchenne muscular dystrophy (1 paper, 2018). Duchenne muscular dystrophy (DMD) is a neuromuscular disease characterized by rapidly progressive muscle weakness and wasting due to degeneration of skeletal, smooth and cardiac muscle. "In addition, low ADIPOQ expression associates with degenerative muscle disease, such as Duchenne muscular dystrophy." (PMID 30241458, 2018).
endometritis (1 paper, 2020). An acute or chronic, usually bacterial infectious process affecting the endometrium. "Therefore, ADIPOQ and RARRES2 represent suitable biomarkers able to provide an early diagnosis of subclinical endometritis and predict the risk of persistence of uterine inflammation." (PMID 32567551, 2020). "Therefore, endometrial cis and/or trans ADIPOQ signalling may be up-regulated following LPS injury, which may convey early predictive information regarding the establishment of endometritis." (PMID 32567551, 2020). "However, unlike ADIPOQ, RARRES2 ROC curve and OR analysis revealed that only uterine fluid RARRES2 concentrations were suitable to discriminate persistent endometritis cows at 45 DPP." (PMID 32567551, 2020).
epididymitis (1 paper, 2023). Inflammation of the epididymis. "Rahmanifar and Tabandeh reported that ADIPOQ, ADIPOR1 and ADIPOR2 transcripts are present in the testes, epididymitis, and vesicular and bulbourethral glands." (PMID 36830390, 2023).
fracture (1 paper, 2018). "To further ascertain whether this differential expression was specifically present in AIS patients, we analyzed ADIPOQ mRNA and H19 expression in muscle tissues obtained from a series of 16 age-matched patients undergoing spinal surgery for thoracic spinal fracture." (PMID 30241458, 2018).
Glucose intolerance (1 paper, 2022). Glucose intolerance (GI) can be defined as dysglycemia that comprises both prediabetes and diabetes. "In contrast, seipin deletion under the constitutive adipoQ promoter does not lead to glucose intolerance, but a 48 h high-fat diet (HFD) feeding is sufficient to trigger glucose intolerance, suggesting that those mice are highly susceptible to metabolic complications." (PMID 35054926, 2022).
gout (1 paper, 2015). A condition characterized by painful swelling of the joints, which is caused by deposition of urate crystals. "The objective of the present study was to determine the levels of Lep and AdipoQ in patients with gout under regular treatment and its relationship with the presence of MetS and joint inflammatory activity." (PMID 26131838, 2015). "This study suggests that in patients with gout, concentrations of Lep and AdipoQ are more in line with the metabolic state than with clinical disease activity." (PMID 26131838, 2015). "These Lep and AdipoQ (especially Lep) values related to MetS course had been previously reported in patients with MetS, without gout." (PMID 26131838, 2015).
Hearing impairment (1 paper, 2023). A decreased magnitude of the sensory perception of sound. "Murohara reported that adiponectin supplementation via adenoviral vectors and the jugular vein reversed hearing impairment in 6-week-old wild-type and AdipoQ-KO mice aged 6 weeks by 8 weeks of age." (PMID 36810096, 2023).
hemochromatosis (1 paper, 2017). A disorder of iron metabolism characterized by a triad of HEMOSIDEROSIS; LIVER CIRRHOSIS; and DIABETES MELLITUS. "Rs1853021 in LPA and rs2802292 in FOXO3 (p = 0.052) and rs1800562 in HFE (hemochromatosis) and rs56354395 in ADIPOQ (adiponectin, C1Q and collagen domain containing) (p = 0.059)." (PMID 28206976, 2017).
intracranial aneurysms (1 paper, 2025). "Growing evidence suggests that ADIPOQ is involved in inflammatory responses and vascular remodeling, processes directly implicated in the development of intracranial aneurysms (IA)." (PMID 40313967, 2025).
Lipedema (1 paper, 2020). Disorder of adipose tissue characterized by symmetric and bilateral enlargement of the lower extremities due to abnormal deposition of subcutaneous fat often in obese women. "We analyzed the expression of the primary adipogenic (ADIPOQ, LPL, PPAR-γ and Glut4) and ECM-remodeling (collagen, FN, LN, ITAGA5, MMP2, 9 and 11) markers at the transcriptional level and by immunohistochemistry in 3D spheroids derived from ASCs from both lipedema and healthy individuals." (PMID 33171717, 2020).
lipoma (1 paper, 2018). A benign, usually painless, well-circumscribed lipomatous tumor composed of adipose tissue. "Although there are no studies on gene expression in isolated cells some research groups investigated the differences in expression of ADIPOQ, LEP and PPARG, RUNX2 and BGLAP in lipoma tissue and compared it with normal adipose tissue." (PMID 30544806, 2018).
liver failure (1 paper, 2015). A liver disease characterized by the liver losing or has lost all of its function. "It is also interesting to note that ADIPOQ, β-NGF, CXCL1, CXCL9, CXCL12, IL-16, and PECAM-1 are up-expressed only in those CHC and HCC patients who present a liver failure, and, hence, linkable to the necro-inflammatory activity of the liver." (PMID 26226632, 2015).
mastitis (1 paper, 2025). Inflammation of breast tissue during lactation or postpartum due to an obstructed duct or infection. "Comprehensive analysis indicates that ADIPOQ is a significant molecular target in the cytokine responses related to clinical bovine mastitis." (PMID 40243473, 2025). "However, studies on the role of ADIPOQ in dairy mastitis are lacking." (PMID 40243473, 2025).
melanoma (1 paper, 2023). A malignant, usually aggressive tumor composed of atypical, neoplastic melanocytes. "The DPP4+ASC subtype is associated with a poor prognosis in PAAD and KIRC patients, while the ADIPOQ+Adi subtype is linked to poor survival in melanoma and BRCA patients." (PMID 37454080, 2023).
microtia (1 paper, 2024). "This is coherent with the result in IHC that CDH13 and ADIPOQ are lower in microtia patients." (PMID 38802922, 2024). "The verification of the multi-omics results with other microtia patients identified that ALDOB, ADIPOQ, CDH13 and TASP1, and oxidative stress may play a role in chondrogenic anomalies." (PMID 38802922, 2024).
osteoarthritis (1 paper, 2019). A noninflammatory degenerative joint disease occurring chiefly in older persons, characterized by degeneration of the articular cartilage, hypertrophy of bone at the margins and changes in the synovial membrane. "The statistical results showed that the expression levels of ADIPOQ, IL6, and CXCR1 in the synovium of osteoarthritis were significantly increased (p <0.05)." (PMID 31139654, 2019). "The qRT-PCR results showed that the expression levels of ADIPOQ, IL6, and CXCR1 in the synovium of osteoarthritis were significantly increased (p <0.05)." (PMID 31139654, 2019).
ovarian disease (1 paper, 2021). "In addition, four ovarian DEGs (ABCA5, ADIPOQ, ITGAV, and PPARG) in the FM_1-vs-NM_1 group are associated with negative regulation of macrophage-derived foam cell differentiation and are all involved in ovarian disease." (PMID 35052428, 2021).
schizophrenia (1 paper, 2017). A major psychotic disorder characterized by abnormalities in the perception or expression of reality. "In Conclusion, our findings suggest the role of TOX, ADIPOQ and BDNF in weight and WHR gain induced by atypical antipsychotics in schizophrenia subjects." (PMID 28327672, 2017).
schwannoma (1 paper, 2025). A benign, usually encapsulated slow growing tumor composed of Schwann cells. "Similarly, CYBB, commonly linked to oxidative burst in phagocytes, and ADIPOQ, associated with metabolic and inflammatory signaling, have not been connected to schwannoma biology." (PMID 41231782, 2025).
Sleep apnea (1 paper, 2023). An intermittent cessation of airflow at the mouth and nose during sleep is known as sleep apnea. "The expression levels of hub genes and sleep apnea-related genes were significantly correlated, among which KILH4 and BCHE were significantly positively correlated (Pearson r = 0.897), OR9A4 Significantly negative correlation with ADIPOQ (Pearson r = −0.762)." (PMID 38077447, 2023).
Uterine leiomyoma (1 paper, 2021). The presence of a leiomyoma of the uterus. "Until now, to our best knowledge ADIPOQ (NM_004797.4):c.214+62G>T (rs1501299) still has not been analyzed in uterine leiomyomas." (PMID 35250389, 2021).
yang deficiency (1 paper, 2022). Yang deficiency is a concept from traditional Chinese medicine. "In addition, several disease related proteins were exclusively involved in the PPI network of the Yang deficiency group, such as adiponectin receptor protein 1 (ADIPOQ), mannose-binding protein C (MBL2), and insulin-like growth factor-binding protein 4 (IGFBP4)." (PMID 35087594, 2022). "We found that ADIPOQ was upregulated 3.26 times in Yang deficiency samples, while no significant change was detected in Qi-yin samples compared with the healthy controls." (PMID 35087594, 2022). "Considering the different regulated expression levels, ADIPOQ, MBL2, and IGFBP4 might be potential biomarkers for differentiation and identification of Yang deficiency and Qi-yin deficiency syndromes of HF." (PMID 35087594, 2022).
cancer (45 papers, 2007 to 2025). A tumor composed of atypical neoplastic, often pleomorphic cells that invade other tissues. "Ultimately, our aim was to investigate the potential mechanisms underlying the cancer-promoting effects of ADIPOQ+CAAs." (PMID 37454080, 2023). "ADIPOQ is secreted by adipocytes in the tumor microenvironment, is widely present in the intestinal tract, and has been shown to activate cytotoxic autophagy induced by cancer cells; thus, elevated ADIPOQ levels are associated with decreased cancer growth." (PMID 36591255, 2022). "Several previous meta-analyses have focused on the associations between ADIPOQ polymorphisms and cancer risk." (PMID 32588903, 2020). "Adiponectin protein and some variations in its gene, ADIPOQ have recently been associated with cancer because they regulate glucose and lipid metabolism as well as anti-apoptotic and anti-inflammatory proteins." (PMID 30883598, 2019). "Several polymorphisms in ADIPOQ and its receptor genes have been demonstrated to influence the expression of these genes and subsequent cancer risk." (PMID 22087284, 2011). "Our findings revealed a significant decrease in adiponectin levels (encoded by ADIPOQ), which are known for their inhibitory effects on cancer, while there was a marked increase in leptin levels (encoded by LEP), known for their growth-promoting effects, in MIIP+/− CM-treated adipocytes." (PMID 38245780, 2024). "ADIPOQ gene polymorphism was closely related to cancer risk by influencing plasma level of ADIPOQ." (PMID 34742352, 2021). "ADIPOQ is one of the most important adipocytokines secreted by adipocytes (Parida, Siddharth & Sharma, 2019), and the polymorphisms of ADIPOQ have been reported to correlate with several types of cancer, including colorectal and breast cancers." (PMID 33717664, 2021). "Leptin and AdipoQ may not only be closely related to the occurrence of cancer, but closely associated with the prognosis of cancer." (PMID 33256658, 2020). "However, to date, these have been few studies addressing the role of genetic variants in ADIPOQ and its receptor genes as cancer susceptibility factors in Chinese population." (PMID 22087284, 2011). "Several cancer-associated adipocyte subtypes, namely DPP4+ adipocytes in visceral adipose and ADIPOQ+ adipocytes in subcutaneous adipose, are identified." (PMID 37454080, 2023). "In order to adequately address ADIPOQ’s numerous roles in cancer and immunity, the research focus has shifted toward its receptors: ADIPOR1, ADIPOR2 and T-cadherin." (PMID 36429712, 2022). "Even though there is a body of evidence regarding the association of ADIPOQ and TNF-α, only a few studies have addressed the relationship between this immune mediator and ADIPOQ receptors, especially in cancer." (PMID 36429712, 2022). "ADIPOQ levels were correlated to various kinds of cancers, but its role has not been well understood, yet." (PMID 32245227, 2020). "Our research provides clues for detecting the molecular mechanism of the function of ADIPOQ in cancer." (PMID 32588903, 2020). "Many studies have found that AdipoQ has significant anti-proliferative, anti-cancer activity, and anti-inflammatory effects." (PMID 33256658, 2020). "In another study, it has been shown that patients with low ADIPOQ levels had a significantly increased likelihood of cancer recurrence." (PMID 25923423, 2015). "AdipoQ mediates cell growth and apoptosis, and may be an important driver of progression in several cancers." (PMID 39349421, 2024). "AdipoQ levels are low in patients with breast, uterine, ovarian, prostate cancers, and AdipoQ may halt tumor progression." (PMID 39349421, 2024). "Furthermore, we investigated the tumor-promoting mechanism of ADIPOQ+CAAs, which provides a deeper understanding of the role of adipocytes in cancer progression and provides new insights for the development of targeted therapies." (PMID 37454080, 2023). "ADIPOQ’s purpose in cancer development therefore still remains unresolved." (PMID 36429712, 2022).
cancer (continued). "Finally, subjects were genotyped for polymorphisms of interest, considering that ADIPOQ and ADIPOR1 SNPs can cause the improper functioning of the ADIPOQ axis and have important clinical implications for cancer development." (PMID 36429712, 2022). "Another study reported that variation in the ADIPOQ gene has effects on other types of cancer." (PMID 32977760, 2020). "Indeed, even though the preponderance of evidence suggests an inverse correlation of serum ADIPOQ levels with cancer, other studies correlated the increase of ADIPOQ levels with cancer progression." (PMID 32245227, 2020). "Moreover, epidemiological studies have found underexpression of ADIPOQ existing in a wide variety of human cancers, which strongly supported the importance of ADIPOQ in suppression of cancer initiation and development." (PMID 22087284, 2011). "Indeed, ADIPOQ inhibits proliferation and promotes apoptosis in different types of cancer cells." (PMID 35757418, 2022). "In this study, we focus on the epigenetic regulation of four genes—ADIPOQ, GAS5, GATA4, and YAP1—selected for their established roles in fundamental cancer pathways and their potential for methylation-mediated dysregulation in TNBC." (PMID 41226688, 2025). "This component features COL10A1, ITIH5, ADIPOQ, ADAMTS5, GPC3, SFRP1, and RARRES2 genes, pointing to their involvement in cancer-related cellular structures." (PMID 38253993, 2024). "Consequently, a total of 11 studies were enrolled in the meta-analysis investigating the relationships between LEP/LEPR/ADIPOQ/ADIPOR1/ADIPOR2 variants and total PCa risk, and ten studies were included in the pooled-review discussing these polymorphisms' impact on the aggressiveness of cancer." (PMID 27768592, 2016). "We found six genes, ADIPOQ, DKK1, IGF1, IGF1R, IGF2, and PLAUR were shared by all the four cancers." (PMID 28676692, 2017). "On the other hand the serum levels of ADIPOQ, CXCL9, PECAM-1, Prolactin, sVEGFR-1 and sVEGFR-2 in the T2D-HCC patients were higher than those of patients with only T2D while they were similar to those of HCC patients, confirming that these proteins are specific for the cancer presence." (PMID 26226632, 2015).